PRSS2 (serine protease 2)
Description:
In the ileum, may be involved in defensin processing, including DEFA5.
Synonyms: TRY2; TRYP2; TRY8
Tractability: Small molecule: a high-quality ligand is known. Antibody: its Gene Ontology location is reachable by antibodies, with high confidence; UniProt places it where antibodies can reach, with medium confidence; UniProt predicts a signal peptide or a membrane-spanning region. PROTAC: a small molecule that binds it is known.
Target class: Serine protease; Enzyme; Serine protease PA clan; Serine protease S1A subfamily; Protease
Gene: Protein-coding gene on chromosome 7 (142,760,398 to 142,774,564, forward strand). Ensembl gene ENSG00000275896.
Subcellular location: Secreted, extracellular space
Subcellular location (Human Protein Atlas): Vesicles; Endoplasmic reticulum; Predicted to be secreted
Pathways (Reactome):
Immune System: Alpha-defensins; Antimicrobial peptides; Neutrophil degranulation
Extracellular matrix organization: Activation of Matrix Metalloproteinases; Collagen degradation
Gene Ontology:
Molecular function: calcium ion binding; protein binding; serine-type endopeptidase activity; metalloendopeptidase activity; serine-type peptidase activity
Biological process: collagen catabolic process; proteolysis; antimicrobial humoral response; extracellular matrix disassembly; positive regulation of cell adhesion; positive regulation of cell growth
Cellular component: extracellular region; azurophil granule lumen; extracellular matrix
Genetic constraint (gnomAD): Loss-of-function variants: 18 observed, 16.7 expected, observed/expected ratio (o/e) 1.08, 90% interval 0.74 to 1.59. The upper end of that interval is the gene's LOEUF score, 1.59, which puts it in group 6 of 6, group 1 being the genes least tolerant of losing a copy. Missense variants: 273 observed, 220.7 expected, observed/expected ratio (o/e) 1.24, 90% interval 1.12 to 1.37. Synonymous variants: 97 observed, 82 expected, observed/expected ratio (o/e) 1.18, 90% interval 1 to 1.4.
Homologues: Orthologues: chimpanzee PRSS2 (99% identical), macaque PRSS2 (84% identical), pig PRSS2 (83% identical), mouse Try10 (78% identical), mouse Try4 (77% identical), mouse Try5 (77% identical), rat Prss2 (77% identical), mouse Prss3l (77% identical), rat Prss3 (77% identical), mouse Prss1 (77% identical), mouse Prss2 (77% identical), mouse Prss3 (77% identical), and 7 more. Paralogues in human: PRSS1 (89% identical), PRSS3 (87% identical), PLAU (40% identical).
Diseases named in the same sentence as PRSS2 in open-access papers:
PRSS2 is named in the same sentence as 44 diseases in open-access papers, as found by Europe PMC text mining. Sharing a sentence is not in itself a finding about the gene and the disease. The quoted sentences say what the papers report.
pancreatitis (20 papers, 2011 to 2025). Inflammation of the pancreas. "Perhaps the autoimmune conditions in T1D hinder a regulation for PRSS2, causing higher concentration to stay within the pancreas, to eventually cause the pancreatitis." (PMID 39897058, 2025). "PRSS2, which encodes the digestive enzyme trypsin 2, has been mainly studied in the context of pancreatitis." (PMID 38288591, 2024). "Interestingly, a loss-of-function mutation (p.G191R) in anionic trypsinogen gene (PRSS2) has been reported protective against developing pancreatitis in European, Japan and Indian populations." (PMID 26820620, 2016). "Next Generation Sequencing was performed to analyze a panel of nine genes associated with pancreatitis (CaSR, CFTR, CPA1, CTRC, CTSB, KRT8, PRSS1, PRSS2, and SPINK1)." (PMID 38927485, 2024). "We examined the effect of PRSS2 in pancreatic tumor growth and progression due to the reports that PRSS2 overexpression is a contributing factor to pancreatitis, which is a precursor lesion for pancreatic cancer." (PMID 36575174, 2022). "Although this gene is not directly involved in these pathways, PRSS2 is associated with inflammatory conditions in humans such as pancreatitis and inflammatory bowel disease." (PMID 36873940, 2023). "Mutations in other genes such as anionic trypsinogen (PRSS2), the serine protease inhibitor Kazal type 1 (SPINK1), CFTR, chymotrypsinogen C (CTRC) and calcium-sensing receptor (CASR) are also associated with an increased risk for pancreatitis." (PMID 22133269, 2011). "Finally, transgenic expression of human PRSS2 exacerbates pancreatitis in mice." (PMID 33202925, 2020). "While, the 2 patients with CF without pancreatitis had, in IPAT genes, a heterozygous PRSS1/PRSS2 hybrid mutation and a heterozygous missense mutation of CTRC, respectively." (PMID 30134826, 2018).
chronic pancreatitis (8 papers, 2006 to 2024). A chronic inflammatory process causing damage and fibrosis of the pancreatic parenchyma. "Increasing the copy number of PRSS2 gene, which encodes trypsinogen, is associated with chronic pancreatitis in humans." (PMID 31618984, 2019). "Taken together, the G191R variant of PRSS2 mitigates intrapancreatic trypsin activity and thereby plays a protective role against chronic pancreatitis." (PMID 17204147, 2007). "On the other hand, a loss of function mutation of anionic trypsinogen (PRSS2) protects against chronic pancreatitis." (PMID 17069643, 2006). "In the last decade, several authors identified associations of chronic pancreatitis (idiopathic and hereditary) to other genes, such as the anionic trypsinogen (PRSS2), the Serine Protease Inhibitor, Kazal type 1 (SPINK1) and the cystic fibrosis transmembrane conductance regulator (CFTR)." (PMID 17204147, 2007). "serine protease 2 can reduce trypsin activity and protect chronic pancreatitis." (PMID 37022096, 2023). "Other genes, such as the anionic trypsinogen (PRSS2), the serine protease inhibitor, Kazal type 1 (SPINK1) and the cystic fibrosis transmembrane conductance regulator (CFTR) have been found to be associated with chronic pancreatitis (idiopathic and hereditary) as well." (PMID 17204147, 2007).
COVID-19 (5 papers, 2021 to 2025). A disease caused by infection with severe acute respiratory syndrome coronavirus 2. "The modulation of transmembrane serine protease 2 expression by sex steroids has been put forward as a possible reason for male predominance noted among the COVID-19 population." (PMID 38793660, 2024). "Narsoplimab, a high-affinity fully human immunoglobulin gamma 4 (IgG4), has been reported to block the lectin pathway by binding to mannan-binding lectin-associated serine protease-2 (MASP-2), which binds to COVID-19 N protein in disease progression." (PMID 34199430, 2021). "Among them the mannose binding lectin serine protease 2 (MASP-2) has also been implicated in the altered lectin complement pathway resulting in accelerated inflammatory responses and lung damages involved in COVID-19 pathogenesis." (PMID 33435561, 2021). "Several proteins related to the complement cascade have been shown to be dysregulated in PLWH with COVID-19; for example, complement factor D (CFD), mannan-binding lectin serine protease 2, and VTN levels were significantly elevated compared to those in PLWH and HCs." (PMID 40568587, 2025).
breast carcinoma (3 papers, 2022 to 2023). "In breast cancer, the expression of serine protease 2 induced by C-terminal-binding protein 1 is associated with tumor progression and metastasis." (PMID 37022096, 2023). "We then analyzed a set of human breast cancer cell lines for PRSS2 expression and found that its expression level correlated with the metastatic potential of the cell lines." (PMID 36575174, 2022). "To determine if PRSS2 was required for the repression of Tsp-1 we silenced its expression in the highly metastatic breast cancer cell line SUM159 via lentiviral transduction of shRNA specific for PRSS2." (PMID 36575174, 2022). "But no previous study has reported the role of PRSS2, SPPL2C and RHBDL1 in breast cancer, thus this study may report the potential role of these genes as independent prognostic predictors in breast cancer for the first time." (PMID 36993976, 2023).
gastric cancer (3 papers, 2010 to 2025). A primary or metastatic malignant neoplasm involving the stomach. "However, the expression of serine protease 2 in blood samples of gastric cancer patients and healthy people needs further analysis to evaluate its early clinical diagnostic value for gastric cancer." (PMID 37022096, 2023). "High expression of PRSS2 in gastric cancer is associated with less T cell infiltration." (PMID 37022096, 2023). "In contrast to gastric cancer, where PRSS2 promotes tumor invasiveness activity, high PRSS2 expression in PTC aligns with enhanced antitumor immunity activity." (PMID 41141930, 2025). "serine protease 2 is a serine protease that can degrade extracellular matrix, activate other proteases related to cancer invasion, and promote the development of gastric cancer." (PMID 37022096, 2023). "Previous studies have shown that serine protease 2 is up-regulated in gastric cancer tissue and is an independent prognostic indicator after gastric cancer surgery." (PMID 37022096, 2023). "However, previous studies have reported that elevated PRSS2 expression correlates with poor prognosis in gastric, breast, and prostate cancers, and promotes epithelial–mesenchymal transition in gastric cancer by upregulating MMP-9." (PMID 41141930, 2025). "The results showed that PRSS2 were related to gastric cancer OS." (PMID 37022096, 2023). "However, the function of serine protease 2 (PRSS2) in gastric cancer (GC) is still unknown." (PMID 37022096, 2023).
pancreatic cancer (3 papers, 2022 to 2023). "serine protease 2 has been proved to be associated with the development of tongue carcinoma, pancreatic carcinoma, colorectal carcinoma and ovarian carcinoma." (PMID 37022096, 2023). "In addition, serine protease 2 can be used as the downstream target of activated K-RAS oncogene to promote the occurrence of pancreatic cancer." (PMID 37022096, 2023). "The high expression of serine protease 2 in pancreatic carcinoma is related to T phase." (PMID 37022096, 2023). "Strikingly, the knockdown of PRSS2 in tumor cells and knockout of LRP1 in myeloid cells potently inhibited tumor growth in mouse models of breast and pancreatic cancer, with tumors having higher levels of Tsp-1 in the TME." (PMID 36575174, 2022).
colorectal cancer (2 papers, 2020 to 2023). A primary or metastatic malignant neoplasm that affects the colon or rectum. "These included PRSS2, EPHB6 and FABP4, which showed correlation with colorectal cancer prognosis, whereas high expression of these genes was related to poor prognosis." (PMID 32033604, 2020).
Hereditary pancreatitis (2 papers, 2013 to 2016). "Gene conversion events between PRSS1 and PRSS2 or between PRSS1 and the pseudogene PRSS3P2 were shown to generate pathogenic alleles that cause hereditary pancreatitis." (PMID 27999401, 2016).
insulinoma (2 papers, 2025). "Supporting this, a study on canine insulinoma metastases reported a 20–70-fold upregulation of PRSS2 transcripts, accompanied by localized expression of CD40–CD40L in the tumor microenvironment." (PMID 41141930, 2025).
ovarian carcinoma (2 papers, 2022 to 2023). A malignant neoplasm originating from the surface ovarian epithelium. "PRSS2 has been found at elevated levels in tissue and serum of gastric, pancreatic, prostate, and ovarian cancer patients." (PMID 36575174, 2022).
prostate carcinoma (2 papers, 2022 to 2025). A carcinoma that arises from epithelial cells of the prostate gland. "And, high PRSS2 expression is strongly associated with poor prognosis in gastric, breast, and prostate cancers." (PMID 41141930, 2025). "Finally, by univariate survival analyses of castration resistance prostate cancer (n = 32), strong PRSS2 expression was associated with a shorter time from diagnosis to death (P = 0.006)." (PMID 36575174, 2022). "Specifically, prostate cancer patients with low CD8 +/strong PRSS2 expression or high FoxP3 +/strong PRSS2 expression had significantly poorer outcome." (PMID 36575174, 2022). "This hypothesis was born out by the observations that PRSS2 expression negatively correlates with PSAP expression in prostate cancer." (PMID 36575174, 2022). "To determine whether PRSS2 has clinical relevance as a potential therapeutic target, we evaluated its expression by immunohistochemistry in series of human breast and prostate cancers." (PMID 36575174, 2022). "Critically, the experimental findings that PRSS2 is required for efficient tumor growth were validated by the observation that PRSS2 expression correlates with aggressive clinical features such as angiogenesis, tumor cell proliferation, disease progression, and survival in prostate cancer patients." (PMID 36575174, 2022). "The observations that more aggressive breast and prostate cancer cell lines express higher levels of PRSS2 than their less metastatic counterparts coupled with the corroboration of these findings in patient samples, led us to hypothesize that disrupting PRSS2 expression could inhibit tumor growth." (PMID 36575174, 2022).
viral infection (2 papers, 2024). "Mannan-binding lectin–associated serine protease 2 co-activates the lectin pathway of the complement in response to several viral infections." (PMID 38225547, 2024).
Cachexia (1 paper, 2020). Severe weight loss, wasting of muscle, loss of appetite, and general debility related to a chronic disease. "Four were common for local/cachexia (C1R, PRKCG, ELANE, SOST: all oppositely regulated) and four for metastatic/cachexia (SERPINA6, PDGFRA, PRSS2, PRSS1: all consistently changed), suggesting that stage and cachexia status might be molecularly separable." (PMID 33334063, 2020).
cervical cancer (1 paper, 2015). A primary or metastatic malignant neoplasm involving the cervix. "BUD31 and PRSS2 belong to chromosomes 7, there are known changes of this chromosome in cervical cancer." (PMID 26388997, 2015).
cholangiocarcinoma (1 paper, 2024). A carcinoma that arises from the intrahepatic biliary tree (intrahepatic cholangiocarcinoma) or from the junction, or adjacent to the junction, of the right and left hepatic ducts (hilar cholangiocarcinoma). "We aimed to investigate the potential antitumor effect of upamostat and opaganib, individually and in combination, on CCA patient-derived xenografts (PDX) in nude mice using PAX165, a cholangiocarcinoma PDX that expresses substantial levels of SPHK2, PRSS1, PRSS2, and PRSS3." (PMID 38473407, 2024).
Constipation (1 paper, 2024). Infrequent or difficult evacuation of feces. "First, in the present study, the PRSS2 gene encoded trypsinogen-2 (anionic trypsin) was downregulated 94.18-fold in C3 deficiency-induced constipation." (PMID 39273477, 2024).
diabetes (1 paper, 2026). "SHBG and PRSS2 might explain the beneficial association with IHD; testosterone, SHBG, CCL5, CNDP1, F11, LCN2, and THBS4 might explain the association with diabetes, which provides insights for drug development." (PMID 41882153, 2026).
kidney transplant (1 paper, 2025). A surgical procedure in which one or both kidneys from a donor are implanted into a recipient. "Moreover, PRSS2 is involved in allograft rejection; serum PRSS2 markedly increases during chronic antibody-mediated rejection in kidney transplant recipients." (PMID 41141930, 2025).
lung carcinoma (1 paper, 2023). "Moreover, we demonstrated that SS induced the high expression of PRSS3, but not PRSS1 or PRSS2, in circulating lung cancer cells to facilitate metastasis, suggesting a crucial role of PRSS3 in metastasis‐initiating CTCs." (PMID 37395651, 2023).
mastitis (1 paper, 2025). Inflammation of breast tissue during lactation or postpartum due to an obstructed duct or infection. "Candidate genes identified in Angus include the neurotrophic receptor tyrosine kinase 2 (NTRK2) that has been implicated with the sire conception rate in Holstein cattle, and MBL associated serine protease 2 (MASP2) was associated with mastitis and milk production in Chinese Holstein cattle." (PMID 40424241, 2025).
mycoses (1 paper, 2025). "Additionally, among these 32 DEPs, 18 were shared with mycoses but not with AA in the UK Biobank, among which PRSS2 was the most significant." (PMID 40822752, 2025).
schistosomiasis (1 paper, 2018). An infectious disease caused by parasitic trematodes of the genus Schistosoma that colonize human blood vessels and release eggs that can cause granulomatous reactions leading to acute (swimmer's itch or acute schistosomiasis syndrome) or chronic disease. "Here, we characterize the structural and proteolytic attributes of serine protease 2 (SmSP2) from Schistosoma mansoni, one of the major species responsible for the tropical infectious disease, schistosomiasis." (PMID 29677188, 2018).
T-cell acute lymphoblastic leukemia (1 paper, 2025). Acute lymphoblastic leukemia of T-cell origin. "For example, in Philadelphia chromosome-negative adult T-cell acute lymphoblastic leukemia, biallelic deletion of PRSS1 and PRSS2 has been observed in patients with clonal rearrangements within the TCRβ locus." (PMID 41141930, 2025).
thyroid cancer (1 paper, 2025). "Since serum protein levels reflect cumulative expression from various tissues, the modest upregulation of PRSS2 in thyroid cancer tissue (approximately 2–4-fold compared to paracancerous tissue) may be insufficient to notably alter serum concentrations and can be masked by high-expression tissues." (PMID 41141930, 2025).
triple-negative breast carcinoma (1 paper, 2022). An invasive breast carcinoma which is negative for expression of estrogen receptor (ER), progesterone receptor (PR), and human epidermal growth factor receptor 2 (HER2). "We injected wild-type C57BL6/J mice and LysM-Cre-LRP1−/− mice with the murine triple-negative breast cancer cell line E0771, which express similar levels of PRSS2 to Pan02 cells and even greater levels than SUM159 cells." (PMID 36575174, 2022). "Additionally, SUM159, a metastatic triple-negative breast cancer cell line expresses significantly higher levels of PRSS2 than the ER + and non-metastatic cell line MCF7." (PMID 36575174, 2022).